LDHC (lactate dehydrogenase C)
Diseases named in the same sentence as LDHC in open-access papers (continued):
Sharing a sentence is not in itself a finding about the gene and the disease.
breast cancer (continued). "Using multiple breast cancer cell line models (MDA-MB-468, BT-549, HCC-1954), we identified STAT-3 signaling to be a cell line-dependent factor determining cancer cell survival following LDHC silencing." (PMID 39001513, 2024). "We previously reported that lactate dehydrogenase C (LDHC) plays a key role in regulating genomic stability and that targeting LDHC significantly improved treatment response to DNA damage response drugs in breast cancer." (PMID 39001513, 2024). "In contrast to what we observed in basal-like breast cancer cells, the depletion of LDHC in the Her2-enriched breast cancer cell line HCC-1954 did not induce DNA damage or reduce short- or long-term cancer cell survival." (PMID 39001513, 2024). "Interrogation of breast cancer patient cohorts from The Cancer Genome Atlas (TCGA) and Molecular Taxonomy of Breast Cancer International Consortium (METABRIC) indicate that upregulation of LDHC expression correlates with unfavorable prognosis." (PMID 34050611, 2022). "Given the expression of LDHC in breast tumors, future studies are needed to evaluate the presence of pre-existing LDHC41−55 and LDHC288−303-reactive T cells in the peripheral blood of breast cancer patients." (PMID 31932876, 2020). "LDHC expression has been detected in different tumor types at varying degrees with frequencies up to 100% in lung adenocarcinoma, 83% in cervical cancer, 76% in high-grade serous ovarian carcinoma (HGSC), 44% in melanoma, and 35% in breast cancer." (PMID 31932876, 2020). "Similarly, breast cancer (BC) diagnosis has benefited from research on exosomal proteins, including heat shock protein 70 (HSP70), thrombospondin-1 (TSP1), lactate dehydrogenase C4 (LDH-C4), exo-Anx2, and integrin α6, all of which show diagnostic potential and contribute to disease monitoring." (PMID 40277513, 2025). "While LDHC silencing greatly reduced the cell survival of basal-like breast cancer cells via the downregulation of STAT3 signaling, it exerted the opposite effect in Her2-enriched breast cancer cells, which could be reversed by STAT3 inhibition." (PMID 39001513, 2024). "Indeed, further analyses using a second breast cancer cell line model shows a strong increase in IFN-γ release and cytolytic activity of P11- and P73-primed T cells against BT549 cells with high expression of LDHC (A2 + /high) versus their counterparts after LDHC silencing (A2 + /low)." (PMID 31932876, 2020). "We found that LDHC silencing increased the frequency and extent of polyploidy (≥ 4N) in MDA‐MB‐468 and BT‐549 cells but not in breast cancer cells with inherent low levels of polyploidy (MDA‐MB‐231 and HCC‐1500)." (PMID 34050611, 2022). "The pan-cancer expression of LDHC/LDH-C4 has been assessed, and the results of IHC based on high-throughput tissue microarray analyses suggest the highest positivity rate of LDH-C4 in LUAD (96.7%), followed by breast cancer (BC) (91.55%), and hepatocellular carcinoma (HCC) (55.84%)." (PMID 36408133, 2022). "In order to investigate the role of LDHC in breast cancer, its expression was stably silenced in three basal‐like breast cancer cell lines (MDA‐MB‐468, BT‐549, MDA‐MB‐231) alongside one nonbasal, luminal A breast cancer cell line (HCC‐1500)." (PMID 34050611, 2022). "Using different breast cancer cell lines, we demonstrated that LDHC41−55and LDHC288−303 specific T cells were capable of recognizing and eradicating HLA-A*0201 positive/LDHC positive tumor cells, while no specific cytolytic activity was detected against HLA-A*0201 negative/LDHC positive tumor cells." (PMID 31932876, 2020).
melanoma (10 papers, 2012 to 2025). A malignant, usually aggressive tumor composed of atypical, neoplastic melanocytes. "Similar to our observations in Her2-enriched and triple negative breast cancer, high LDHC expression in melanoma significantly diminished the favorable association between CTL infiltration and overall survival." (PMID 40108668, 2025). "At the same time, intra-tumoral lactate dehydrogenase C isoform (LDHC) activation in melanoma cells provides a metabolic rescue pathway for these cells via the preference for lactate metabolism for ATP generation." (PMID 35565255, 2022). "Another study highlights that LDHC expression is upregulated in the responder population among patients with melanoma undergoing treatment with anti–PD-1 therapy, suggesting that LDHC is a potential predictive biomarker of response to immune checkpoint inhibitor therapy." (PMID 36408133, 2022). "For instance, the LDHC positivity rate reaches 100% (18/18) in lung adenocarcinoma (LUAD), 76% in high-grade serous ovarian carcinomas (HGSC), and 44% in melanoma." (PMID 36408133, 2022).
lung carcinoma (9 papers, 2016 to 2024). "LDHC expression was low in kidney and thyroid cancer tissues and has little variability in lung cancer tissues." (PMID 38291366, 2024). "The transcription factor Sp1 and CREB-mediated overexpression of LDHC promote lung cancer cell proliferation in vitro and metastasis in vivo." (PMID 35574342, 2022). "The combined HR of LDHC in predicting the survival of lung cancer was estimated to be 1.1542 (95% CI: 1.0498–1.2690)." (PMID 35814471, 2022). "LDHC/LDH-C4 is implicated in the occurrence and development of tumor, but there are few studies on LDHC/LDH-C4 and lung cancer, especially the detection of serum and exosomal LDHC in lung cancer." (PMID 35814471, 2022). "Pan-cancer analysis showed that the LDHC mRNA level in pan-cancer was higher than that in normal controls, including lung cancer (LUAD and LUSC)." (PMID 35814471, 2022). "Another study confirms the positivity rate of LDHC at 25% in non–small cell lung cancer (NSCLC) samples (including 102 tumor specimens and seven cell lines)." (PMID 36408133, 2022). "As summarized by Jing W and colleagues, overexpression of LDHC in renal cell and lung cancer cell lines and a lung cancer xenograft mouse model greatly enhances cellular motility through regulation of epithelial-to-mesenchymal transition (EMT) and expression of matrix metalloproteinases." (PMID 36814815, 2023). "However, the expression and clinical significance of LDHC/LDH-C4 in lung cancer remain to be elucidated." (PMID 35814471, 2022). "LDHC is a specific isoenzyme of the LDH family and is overexpressed in lung cancer." (PMID 35574342, 2022).
lung adenocarcinoma (6 papers, 2020 to 2025). A carcinoma that arises from the lung and is characterized by the presence of malignant glandular epithelial cells. "For instance, we identified LDHC which, prior to this study, was almost exclusively observed in testis, and an association with lung adenocarcinoma had only been suggested." (PMID 34391887, 2021). "As a cancer-testis antigen (CTA), human lactate dehydrogenase C4 (LDH-C4) enzyme protein encoded by the LDHC gene has been reported to be involved in the occurrence and development of various malignancies, while its expression and clinical significance in lung adenocarcinoma (LUAD) remain unclear." (PMID 35814471, 2022). "LDHC is a putative oncogene responsible for smoking-related lung adenocarcinoma, particularly in male patients with pleural effusions, indicating that smoking to some extent contributes to altered LDH-C4 levels in male patients." (PMID 36408133, 2022). "Lactate dehydrogenase C (LDHC) is a kind of cancer-testis antigen (CTA) that has been reported to be a biomarker for diagnosis, efficacy evaluation, and recurrence monitoring of lung adenocarcinoma (LUAD)." (PMID 40270965, 2025).
male infertility (6 papers, 2014 to 2025). The inability of the male to effect fertilization of an ovum after a specified period of unprotected intercourse. "Notably, testis-specific LDHC downregulation was also associated with lower phenyllactate in dzo testes, which could be an outcome of male infertility." (PMID 41153950, 2025). "This section will briefly highlight the role of the eight (TNP1, TNP2, PDHA2, LDHC, SPINK2, ODF1, ODF2, and PCDHB3) common DEGs in male infertility as obtained from our findings." (PMID 35207567, 2022). "Several promising biomarkers for male infertility and prostate cancer include ECM1, TEX101, LDHC, TKTL and ACPP proteins, and prostate specific antigen (PSA), TMPRSS2-ETS." (PMID 26097523, 2015).
hepatocellular carcinoma (5 papers, 2020 to 2025). A malignant tumor that arises from hepatocytes. "Circulating levels of LDHC in serum and serum-derived exosomes have been shown to positively correlate with cancer diagnosis, tumor size, and recurrence in breast and hepatocellular carcinoma." (PMID 40108668, 2025).
Infertility (5 papers, 2014 to 2023). "Deficiency/destruction of germline-specific LDHC leads to infertility, including a reduction in sperm ATP content and reduced sperm motility." (PMID 31703718, 2019). "A study revealed that spermatic LDHC levels in normal donors are significantly higher relative to those in infertile patients with impaired sperm motility through qRT-PCR analyses, thereby suggesting LDHC’s involvement in the motility of spermatozoa." (PMID 36408133, 2022). "A number of mouse strains with KOs of sperm-specific metabolic enzymes (phosphoglycerate Kinase 2, glyceraldehyde 3-phosphate dehydrogenase, and lactate dehydrogenase C) display sperm motility defects which correlate to male-specific infertility, but in vivo migration has not been studied." (PMID 37152282, 2023). "For a subset of testis-specific candidates, i.e., TKTL1, LDHC, and PGK2, their germ cell expression was validated and it was demonstrated that such markers could be distinguished between semen from fertile and infertile men." (PMID 26097523, 2015).
breast tumor (4 papers, 2020 to 2025). "Considering both methods, we found that LDHC expression was negatively associated with NK cell infiltration in basal-like breast tumors and positively correlated with B cell infiltration in Her2-enriched breast tumors." (PMID 40108668, 2025). "Furthermore, high expression of LDHC, in particular in basal‐like breast tumors, was associated with adverse overall (HR = 1.33, P value = 0.08) and disease‐specific survival (HR = 1.86, P value = 0.002)." (PMID 34050611, 2022). "We specifically focused on basal-like and Her2-enriched breast tumors as we have previously identified a higher LDHC expression in these tumors compared to luminal breast tumors." (PMID 40108668, 2025). "The variability in expression levels prompted us to investigate LDHC expression across intrinsic molecular breast tumor subtypes." (PMID 34050611, 2022). "Together, these results suggest that LDHC peptides P11 and P73 represent endogenous peptides that are expressed by breast tumor cells and correctly presented within an HLA-A*02 context with a plausible threshold of LDHC expression for cytotoxic CD8 + T cell reactivity." (PMID 31932876, 2020). "Previously, we showed that lactate dehydrogenase C (LDHC) plays an important role in regulating tumor genomic integrity and that targeting LDHC greatly reduces breast tumor cell survival and improves the efficacy of common anti-cancer drugs." (PMID 39001513, 2024). "However, we did find a negative correlation between LDHC expression and NK cell infiltration in basal-like breast tumors, a cell type which is not available for TIMER analysis." (PMID 40108668, 2025).
Obesity (3 papers, 2016 to 2024). Accumulation of substantial excess body fat. "Moreover, two tested CTAs were significantly downregulated in smoking patients (MAGEA1, AE; FBXO39, AE and RE) and one CTA (LDHC) seemed to be upregulated (AE) in patients with obesity." (PMID 27635108, 2016).
prostate carcinoma (3 papers, 2015 to 2022). A carcinoma that arises from epithelial cells of the prostate gland. "Homo sapiens lactate dehydrogenase c (hLdhc) was reported to be expressed in a wide spectrum of tumors, including prostate cancers, and this expression was shown to be regulated by transcription factor Sp1 and CREB as well as promoter CpG island (CGI) methylation." (PMID 29344347, 2018).
renal cell carcinoma (3 papers, 2018 to 2022). "Upregulation of LDHC has been observed in a variety of cancer types and has been associated with a shorter progression free survival in renal cell carcinoma." (PMID 30400835, 2018). "have evaluated LDHC expression levels in 18 pairs of frozen samples from renal cell carcinoma (RCC) patients (18 cancers and 18 corresponding adjacent tissues) by RT-qPCR." (PMID 36408133, 2022). "Hua Y, Liang C, Zhu J, Miao C, Yu Y, Xu A, Zhang J, Li P, Li S, Bao M, Yang J, Qin C, Wang Z. Expression of lactate dehydrogenase C correlates with poor prognosis in renal cell carcinoma." (PMID 30400835, 2018).
Azoospermia (2 papers, 2021 to 2024). Absence of any measurable level of sperm,whereby spermatozoa cannot be observed even after centrifugation of the semen pellet. "Immunoreactive LDHC protein was detectable in TIF samples from eight men with normal spermatogenesis who underwent testis biopsy due to obstructive azoospermia; these samples are from a separate cohort of patients to those used in the mass spectrometry study." (PMID 33565176, 2021). "However, the variation in the levels of LDHC levels, ranging from very low to similar to those with obstructive azoospermia, suggests there could be varying levels of spermatid development in the seminiferous tubules of these individuals." (PMID 33565176, 2021). "Importantly, LDHC levels were significantly reduced in men with nonobstructive azoospermia (P = .03, n = 8/group)." (PMID 33565176, 2021). "LDHC was detectable in TIF from men with intact spermatogenesis, but was significantly reduced in men with nonobstructive azoospermia due to spermatogenic disruption." (PMID 33565176, 2021).
cervical squamous cell carcinoma (2 papers, 2022 to 2023). A squamous cell carcinoma arising from the cervical epithelium. "High expression of LDHC has been associated with poor clinical outcome in the majority of cancer types, and favorable prognosis in a select few cancers such as head and neck squamous cell carcinoma (HNSC) and cervical squamous cell carcinoma and endocervical adenocarcinoma (CESC)." (PMID 36814815, 2023). "The pan-cancer expression of LDHC/LDH-C4 based on TIMER and UALCAN suggests high levels in cervical squamous cell carcinoma and endocervical adenocarcinoma (CESC), ovarian serous cystadenocarcinoma (OV), uveal melanoma (UVM), TGCTs, skin cutaneous melanoma (SKCM), HNSCC, and BC." (PMID 36408133, 2022).
colon cancer (2 papers, 2023 to 2025). "Lactate dehydrogenase C (LDHC, LDHX, CT32) is a CTA that has been shown to be aberrantly expressed in several solid cancers, including breast, lung, renal and colon cancer, and exhibits immunogenic properties." (PMID 40108668, 2025).
food allergies (2 papers, 2025). "Although LDHC and SLC gene families have been studied in asthma, their association with food allergy appears to be a novel observation that extends existing knowledge of allergy-related pathways." (PMID 41153772, 2025). "Notably, the methylation pattern of the LDHC gene emerged as a potential biomarker for predicting food allergies using DNA methylation in this extensive analysis." (PMID 41153772, 2025). "Notably, LDHC gene (lactate dehydrogenase C) has been reported as hypomethylated in CD4+ T cells of children with food allergy." (PMID 41394805, 2025). "Notably, the methylation pattern of the LDHC gene showed significant potential in distinguishing individuals with food allergies from those with food sensitivity." (PMID 41153772, 2025). "LDHC and SLC35G2 methylation profiles show promise as biomarkers for food allergy diagnosis and for predicting treatment response." (PMID 41153772, 2025). "This validation analysis establishes LDHC and SLC35G2 methylation signatures as reproducible biomarker candidates for food allergy diagnosis." (PMID 41153772, 2025).
head and neck squamous cell carcinoma (2 papers, 2016 to 2022). A squamous cell carcinoma that arises from any of the following anatomic sites: lip and oral cavity, nasal cavity, paranasal sinuses, pharynx, larynx, and salivary glands. "have detected the expression of CTAs in 51 cases of head and neck squamous cell carcinoma (HNSCC) and report no positive expression of LDHC mRNA." (PMID 36408133, 2022).
triple-negative breast carcinoma (2 papers, 2025). An invasive breast carcinoma which is negative for expression of estrogen receptor (ER), progesterone receptor (PR), and human epidermal growth factor receptor 2 (HER2). "Therefore, further studies are needed to determine whether the increased CXCL1 levels following LDHC knockdown in triple negative breast cancer cells primarily impact tumor growth or immune cell infiltration and activation." (PMID 40108668, 2025). "In the triple-negative breast cancer MDA-MB-231 cell line, overexpression of LDHC inhibits the function of mitochondrial respiratory chain complexes and reduces mitochondrial outer membrane permeability (MOMP) to limit the release of Cyt c, thereby inhibiting the apoptosis process." (PMID 40860340, 2025).
Allergy (1 paper, 2025). An allergy is an immune response or reaction to substances that are usually not harmful. "This dual-dataset methodology not only strengthens the reliability of the findings but also emphasizes the translational potential of epigenetic biomarkers including LDHC and SLC35G2 in clinical implementations for food allergy diagnosis and treatment." (PMID 41153772, 2025). "These measures will enhance the clinical value of LDHC and SLC35G2 as actionable biomarkers for food allergy management." (PMID 41153772, 2025).
carcinoma in situ (1 paper, 2022). "We hypothesize that these healthy individuals with positive serum LDHC expression may be at high risk of developing tumors and may be in the early stages of tumors or carcinoma in situ that has not yet been clinically diagnosed." (PMID 35814471, 2022).
chronic pancreatitis (1 paper, 2023). A chronic inflammatory process causing damage and fibrosis of the pancreatic parenchyma. "ALDH3B1, ENO1, ALDH2, GAPDH, and LDHC had significant differences among grades, while ALDH3B1, PKM, and ALDH3B2 differed among chronic pancreatitis histories." (PMID 36814901, 2023).
emotional instability (1 paper, 2023). "Of the six gene scores associated with the emotional instability symptom group, we replicated three genes including IFT74, LDHC and TMPO." (PMID 37322117, 2023).
non-small cell lung carcinoma (1 paper, 2020). A group of at least three distinct histological types of lung cancer, including non-small cell squamous cell carcinoma, adenocarcinoma, and large cell carcinoma. "Other studies show that the positive rate of LDHC mRNA expression is 25% in non-small cell lung cancer (NSCLC) tissues, which is similar to the expression levels in adenocarcinoma and squamous cell carcinoma." (PMID 33035196, 2020).
osteosarcoma (1 paper, 2022). A usually aggressive malignant bone-forming mesenchymal neoplasm, predominantly affecting adolescents and young adults. "suggest that LDHC mRNA levels are significantly downregulated in osteosarcoma samples." (PMID 36408133, 2022).
renal carcinoma (1 paper, 2021). A carcinoma arising from the epithelium of the renal parenchyma or the renal pelvis. "The high expression of GAPDH, PSAT1, PGLS, and LDHC indicated a short DFS and a high risk of developing renal cancer." (PMID 33564363, 2021).
schizophrenia (1 paper, 2024). A major psychotic disorder characterized by abnormalities in the perception or expression of reality. "In the lactate shuttle, six (55%) of the significantly altered genes (n = 11) were upregulated: GLUL, LDHC, SLC16A3, SLC1A2, SLC1A3, and SLC2A1, which were collectively expressed in schizophrenia groups at a level of 1.5× higher than in control groups (LFC = 0.58)." (PMID 39125835, 2024).